ENSG00000279073 (novel protein)
Gene: Protein-coding gene on chromosome 9 (137,031,241 to 137,040,436, reverse strand). Ensembl gene ENSG00000279073.
Genetic constraint (gnomAD): Missense variants: 36 observed, 25.83 expected, observed/expected ratio (o/e) 1.39, 90% interval 1.07 to 1.81. Synonymous variants: 10 observed, 9.26 expected, observed/expected ratio (o/e) 1.08, 90% interval 0.66 to 1.74.